Y_RNA (Y RNA )
Gene: Miscellaneous RNA gene on chromosome 15 (43,863,893 to 43,864,005, reverse strand). Ensembl gene ENSG00000200391.
Homologues: Orthologues: chimpanzee Y_RNA (99% identical), macaque Y_RNA (96% identical). Paralogues in human: RNY1 (88% identical), RNY1P11 (88% identical), Y_RNA (88% identical), Y_RNA (87% identical), Y_RNA (86% identical), Y_RNA (85% identical), RNY1P10 (84% identical), Y_RNA (84% identical), Y_RNA (83% identical), RNY1P8 (82% identical), Y_RNA (82% identical), RNY1P7 (81% identical), and 95 more.